SPNS3 (SPNS lysolipid transporter 3, sphingosine-1-phosphate (putative))
Description:
Sphingolipid transporter.
Synonyms: MGC29671; SLC63A3; SLC62A3
Tractability: Antibody: UniProt predicts a signal peptide or a membrane-spanning region.
Gene: Protein-coding gene on chromosome 17 (4,433,940 to 4,488,208, forward strand). Ensembl gene ENSG00000182557.
Subcellular location: Membrane
Gene Ontology:
Molecular function: protein binding; transmembrane transporter activity
Biological process: transmembrane transport
Cellular component: membrane
Genetic constraint (gnomAD): Loss-of-function variants: 50 observed, 50.87 expected, observed/expected ratio (o/e) 0.98, 90% interval 0.78 to 1.24. The upper end of that interval is the gene's LOEUF score, 1.24, which puts it in group 5 of 6, group 1 being the genes least tolerant of losing a copy. Missense variants: 660 observed, 660.38 expected, observed/expected ratio (o/e) 1, 90% interval 0.94 to 1.07. Synonymous variants: 305 observed, 290.65 expected, observed/expected ratio (o/e) 1.05, 90% interval 0.95 to 1.15.
Homologues: Orthologues: chimpanzee SPNS3 (99% identical), macaque SPNS3 (95% identical), guinea pig SPNS3 (83% identical), rabbit SPNS3 (81% identical), mouse Spns3 (79% identical), rat Spns3 (79% identical), pig SPNS3 (75% identical), zebrafish spns3 (48% identical), Drosophila melanogaster spin (42% identical), Caenorhabditis elegans spin-1 (35% identical), Caenorhabditis elegans spin-2 (32% identical), Caenorhabditis elegans spin-4 (32% identical), and 1 more. Paralogues in human: SPNS1 (51% identical), SPNS2 (44% identical).
Diseases named in the same sentence as SPNS3 in open-access papers:
SPNS3 is named in the same sentence as 7 diseases in open-access papers, as found by Europe PMC text mining. Sharing a sentence is not in itself a finding about the gene and the disease. The quoted sentences say what the papers report.
acute myeloid leukemia (2 papers, 2021 to 2025). Acute myeloid leukemia (AML) is a group of neoplasms arising from precursor cells committed to the myeloid cell-line differentiation. "There is limited research on AC127521.1 and LINC02580, but studies have shown that AC127521.1 can promote the malignant biological behavior of acute myeloid leukemia by regulating the expression of SPNS3 mediated by MIR-139." (PMID 38684626, 2025). "SPNS3 expression is significantly high in acute myeloid leukemia (AML) and serves as a survival indicator." (PMID 34608834, 2021). "However, the functions of SPNS3 in acute myeloid leukemia (AML) are unknown." (PMID 34608834, 2021).
asthma (1 paper, 2021). "In the current literatures, SPNS3 is recognized as an atypical solute carrier belonging to the major facilitator superfamily type and participates in sphingolipid pathways to regulate airway hyperresponsiveness and mast cell activation in asthma patients." (PMID 34608834, 2021).
autoimmune disease (1 paper, 2021). A disorder resulting from loss of function or tissue destruction of an organ or multiple organs, arising from humoral or cellular immune responses of the individual to their own tissue constituents. "The top SNV of the CFA5 locus was located in an intron of the sphingolipid transporter 3 (SPNS3) gene for which the paralogous gene (SPNS2) is known to be important in immunological development, and inflammatory and autoimmune diseases." (PMID 33793571, 2021).
lymphoma (1 paper, 2021). A malignant (clonal) proliferation of B- lymphocytes or T- lymphocytes which involves the lymph nodes, bone marrow and/or extranodal sites. "The CFA5 locus is associated with HS and lymphoma risk in BMDs, and the top SNVs of this locus are located in an intron of the SPNS3 gene." (PMID 33793571, 2021). "Thus, SPNS3 is a strong candidate gene that can explain the predisposition to HS and lymphoma." (PMID 33793571, 2021).
neoplasm (2 papers, 2021 to 2025). A benign or malignant tissue growth resulting from uncontrolled cell proliferation. "This suggests that the combined therapy impairs tumor cell survival strategies such as DNA damage response, metabolic maintenance, and immune function (including CCR3, SPNS3, SPPL3, and BTN2A2)." (PMID 41404060, 2025).
SPNS3 also shares sentences with these, for which no sentence is quoted: cancer (1 paper); infection (1).